CDA (cytidine deaminase)
Diseases named in the same sentence as CDA in open-access papers (continued):
Sharing a sentence is not in itself a finding about the gene and the disease.
tumor (continued). "It remains to be explored whether CDA or P2Y6 blockade in combination with ICB might work in all these tumor types." (PMID 38844817, 2024). "Capecitabine, a new prodrug form of 5-FU, is converted into inactive 5’-deoxy-5-fluorocytidine after oral administration, which is converted into 5’-deoxy-5-fluorouridine by cytidine deaminase in hepatocytes and tumor cells, and selectively converted into fluorouracil." (PMID 39092059, 2024). "CDA depletion in combination with anti-PD-1 treatment reduced tumor growth." (PMID 38844817, 2024). "High-throughput screening of a chemical library led to the identification of a naphthol derivative, X55, targeting CDA-deficient tumor cells preferentially, without affecting the growth of non-tumoral cells regardless of CDA expression status." (PMID 35925417, 2022). "Thus, mediating the 5-FU to the tumor cells by CDA is one of the most feasible approaches to direct the drug to the tumor cells, reducing its toxic effects and improving their pharmacokinetic properties." (PMID 36164544, 2022). "The formulation had the potential to show dual functionality; it could inhibit the activity of cytidine deaminase and function as nanozymes for tumor catalytic therapy." (PMID 35740402, 2022). "We found a strong decrease in MAPT levels in response to X55, by more than 50%, in all X55-sensitive CDA-deficient tumor cells tested, whereas X55 treatment did not affect MAPT levels in X55-resistant CDA-deficient tumor cells." (PMID 35925417, 2022). "Interestingly, CDA can be expressed by both intratumor Gammaproteobacteria and tumor cells, and CDA can degrade gemcitabine, leading to drug resistance." (PMID 35406597, 2022). "Finally, advanced tumor stages (stage 3 and stage 4) were characterized by mutations assigned to Signature 2, associated with the activity of APOBEC family of cytidine deaminase." (PMID 35996174, 2022). "Furthermore, CDA staining is extremely heterogeneous between different sites within a tumor and between different patients, which led to difficulties in evaluating the effect of chemotherapy on CDA expression in patients." (PMID 33874986, 2021). "A choice between adjuvant 5-FU based combination therapies (such as FOLFIRINOX) and gemcitabine-based therapy (e.g., GemCap) could be made based on a combination of hENT1 protein and CDA mRNA measured in a resected tumor." (PMID 34830914, 2021). "Patients with impaired CDA activity might develop strong toxicities after administration of cytarabine while CDA overexpression in tumor tissues might reduce the antitumor efficacy of the drug." (PMID 33669053, 2021). "Strong CDA expression in one-third of tumours tested suggests that further evaluation of this potential novel biomarker in future PDAC interventional trials may be of value." (PMID 32350413, 2020). "Strong expression of cytidine deaminase was detected within the tumour." (PMID 31941506, 2020). "Moreover, macrophages isolated from human PDAC were thought to induce tumor cells to produce cytidine deaminase, which metabolizes GEM to promote chemoresistance." (PMID 31139022, 2019). "In tumor cells, for instance, gemcitabine-metabolizing enzyme levels and activity such as CDA, dCK or Nt5c1A/Nt5c3 may explain the discrepancy between high hENT1 level and poor response to gemcitabine." (PMID 31752123, 2019). "With regard to the possible correlation of the enhanced expression of CDA mRNA with demethylation at the CpG methylation sites of its promoter region, we examined the mRNA levels and methylation status of CDA using lyophilized tumor samples of three matched cases (cases 2, 4 and 6)." (PMID 31040918, 2019).
tumor (continued). "These molecules therefore show a decreased cytostatic activity in CDA-overexpressing tumor cells." (PMID 26322268, 2015). "Capecitabine (Xeloda®; Hoffmann La Roche) is an orally administered fluoropyrimidine carbamate, metabolised in liver and tumour by carboxylesterases and cytidine deaminase to 5′-deoxy-5-fluorocytidine (5′-DFCR) and 5′-deoxy-5-fluorouridine (5′-DFUR) respectively." (PMID 23840665, 2013). "The differences between liver and spleen in tumor burden and its reduction by decitabine alone suggested that CDA expression could be substantially higher in murine liver than in spleen." (PMID 23087155, 2012). "Moreover, our bioinformatic analyses in individuals with cancer demonstrate that CDA levels are highest in 11 different tumor types with immunosuppressive features (that is, high in P2RY6, MRC1 and MSR1 levels in macrophages and low in IFNG and PRF levels in CD8+ T cells)." (PMID 38844817, 2024). "In summary, PmTriTNE could activate T cells in the context of the TME, reverse PD‐L1 blockade to directly drive tumor cell lysis, and act synergistically with CDA to initiate an amplified immune cascade and thus achieve long‐term antitumor immunity against cold solid tumors." (PMID 36089659, 2022). "Moreover, whether CDA expression increases after chemotherapy is challenging to determine in vivo since CDA expression was extremely heterogeneous in tumor tissues of patients." (PMID 33874986, 2021). "Therefore, patients with impaired CDA activity might develop strong toxicities after administration of gemcitabine, while CDA overexpression in tumour tissues might reduce the antitumour efficacy of this drug." (PMID 17595663, 2007). "It has been established that PTX can destroy stromal density and inhibit the cytidine deaminase (CDA) that induces the GEM metabolic inactivation via upregulating oxidative stress (HO-1), thereby enhancing the therapeutic delivery of GEM into tumor sites." (PMID 40841472, 2025). "It is then metabolized by cytidine deaminase into 5′-DFUR in both liver and tumor tissues—the final conversion to 5-FU in tumors, facilitated by dThdPase." (PMID 40497987, 2025). "To assess the possible link between CDA expression in cancer cells and ICB resistance in PDAC, we used two mouse PDAC tumor engraftment models: orthotopic KPC tumors and subcutaneous (s.c.)Panc02 tumors." (PMID 38844817, 2024). "These included CDA and CD55, which were upregulated in the tumor cluster and F10 upregulated in the stroma cluster." (PMID 38291365, 2024). "Combining CDA inhibitors with both gemcitabine and anti-PD-1 therapy may have synergic effects, potentiating the cytotoxic impact of gemcitabine on cancer cells and tumor immunogenicity and enabling the immune system to act against the tumor in response to anti-PD-1." (PMID 38844817, 2024). "Cytidine deaminase (CDA) is one of the major enzymes in the metabolism of capecitabine in liver and tumor cells that deaminates cytidine and 2′-deoxycytidine for uracil derivative synthesis required for pyrimidine pathway preservation." (PMID 37754498, 2023). "Firstly, it is converted to intermediate 5′-deoxy-5-fluorocytidine by carboxylesterase in the liver and subsequently to 5′-deoxy-5-fluorouridine by cytidine deaminase (CDA) in liver and tumor cells." (PMID 37754498, 2023). "In baseline primary tumor samples, COSMIC signature 2, thought to arise from cytidine deaminase activity of AID / APOBEC, was significantly enriched in MPR patients compared to patients without MPR (P = 0.006)." (PMID 34937871, 2021). "In the present study we biochemically and kinetically characterized M. hyorhinis-encoded CDA and report on a surprising interaction between mycoplasma CDA and purine nucleoside phosphorylase (PNP) activity in mycoplasma-infected tumor cells." (PMID 26322268, 2015).
tumor (continued). "A CAP-induced decrease in CDA activity could lead to improved anti-tumour efficacy with the GEMCAP combination, but also may explain the increased toxicity associated with the GEMCAP combination in our studies as, in mice, high CDA activity is seen in the intestine." (PMID 23840665, 2013). "Capecitabine is converted by carboxylesterase in the liver to 5′-deoxy-5-fluorocytidine (5′-DFCR), by cytidine deaminase in the liver and tumor tissue to 5′-deoxy-5-fluorouridine (5′-DFUR), and by thymidine phosphorylase (TP) to 5-FU in tumor tissue." (PMID 23822606, 2013). "In this study, we demonstrated that THU acts on some tumor cell lines to be both A) independently cytotoxic and B) to sensitize gemcitabine cytotoxicity through E2F1 in both CDA-high and CDA-low expressing cells." (PMID 22616006, 2012). "Moreover, we observed a significantly higher expression of CDA and a trend towards higher expression of DCK in human tumor samples in comparison to the surrounding stroma." (PMID 38744194, 2024). "Again, CDA depletion increased cytotoxic CD8+ T cell infiltration at the core without affecting their abundance at the tumor rim." (PMID 38844817, 2024). "Several studies provide compelling evidence that MSCs can be genetically engineered to deliver anti-tumor drugs (PTX, DOX) and immunomodulatory factors (IL-12, IL-24, IFN-Υ, IFN-β, TRAIL, PEDF, apotin, CDA/UPRT and CX3CL1) to target cells, thereby conferring anti-tumor/anti-metastatic actions." (PMID 36739406, 2023). "In this tumour-type, tumours arising in older patients were preferentially SBS2-positive (marginal log odds change = 0.051, 95% CI = 0.013–0.095, adjusted LGR p = 0.029), attributed to APOBEC cytidine deaminase activity." (PMID 35017538, 2022). "Again, a significant decrease in MAPT levels was observed in the two X55-sensitive CDA-proficient tumor cells, but not in X55-resistant CDA-proficient tumor cells." (PMID 35925417, 2022). "We then tested the cytotoxicity of X55 on 29 tumor cell lines, nine of which expressed CDA (the other 20 having no CDA expression), and on five nonmalignant cell lines." (PMID 35925417, 2022). "CDA expression did neither correlate with pT considering all samples nor with the proportion of residual tumor cells, pN, latency between neoadjuvant chemotherapy and resection or duration of neoadjuvant chemotherapy in samples after neoadjuvant therapy." (PMID 33874986, 2021). "When comparing the SEQ with the CON treatment arm, strongly positive tumour epithelial CDA staining was evident in 34 tumours and appeared to predict for improved PFS, but not OS associated with SEQ therapy (HR 0.31, 95% CI 0.13–0.70)." (PMID 32350413, 2020). "In in vivo PDAC models of mice, macrophages recruitment to the tumor using CSF1R-antagonist GW2580, enhanced the effect of GEM; the presence of TAMs in the tumor seems to convey resistance to GEM by inducing upregulation of the enzyme cytidine deaminase (CDA)." (PMID 32656079, 2020). "As a pro-drug, GEM has to enter the tumor cell to become active, and a major part of GEM is converted into the inactive metabolite 2′,2′-difluorodeoxyuridine (dFdU) by the deamination effect of cytidine deaminase (CDA)." (PMID 31130654, 2019). "We hypothesise that the correlation of CDA activity with efficacy outcome (OS and PFS) might be the result of differential detoxification of gemcitabine by both the liver and the tumour cells." (PMID 30405211, 2018). "Tissue damage and tumor formation in AID transgenic mice may be triggered by genotoxic and/or mutagenic mechanisms peculiar to activation-induced cytidine deaminase." (PMID 25659078, 2015). "Oral capecitabine passes intact through the intestinal tract, but is converted first by carboxylesterase to 5’-deoxy-5-fluorocytidine (5'-DFCR) in the liver, then by cytidine deaminase to 5’-DFUR in the liver and tumor tissues, and finally by dThdPase to 5-FU in tumors." (PMID 24281184, 2010).
tumor (continued). "Based on the modified immune landscape after tweaking CDA expression in cancer cells and comparable tumor growth of sgNT and sgCda Panc02 cancer cells in immunodeficient (nude) mice, we tested the contribution of CD8+ T cells and macrophages after CDA targeting." (PMID 38844817, 2024). "We then performed the same experiments with CDA-proficient tumor cells and non-malignant cells." (PMID 35925417, 2022). "Thus, MAPT levels decrease by more than 50% in all X55-sensitive tumor cell lines, regardless of their CDA expression status, but not in X55-resistant tumor or nonmalignant cell lines." (PMID 35925417, 2022). "The pharmacokinetics of gemcitabine in tumor cells is regulated by human equilibrative nucleoside transporters (hENTs)-mediated uptake, activation by deoxycytidine kinase (DCK), and inactivation by cytidine deaminase (CDA), deoxycytidylate deaminase (DCTD), and cytosolic 5′-nucleotidases (NT5C1A)." (PMID 33546284, 2021). "Immunohistochemical studies showed that CDA staining was identified primarily but not exclusively in the cellular compartment of tumours, but only strongly positive CDA staining within the tumour epithelial cells predicted for survival benefit with SEQ delivery." (PMID 32350413, 2020). "We next assessed whether the phenotype of the gemR models acquired in vivo differed from drug-sensitive counterparts with respect to expression of proteins involved in gemcitabine transport into tumor cells (hCNT1 and hENT1) or in gemcitabine metabolism (RRM1, RRM2, CDA, dCK)." (PMID 33073205, 2020). "The LC-MS/MS analyses of CAP-treated tumours revealed that the highest DFCR concentrations was 511 μM, within the range tested in this competition assay, supporting that the observed decrease in CDA activity in CAP-treated tumours was not related to a substrate competition." (PMID 23840665, 2013). "Therefore, the tumor stage did not explain the relationship between CDA and survival." (PMID 34830914, 2021). "Promising observations from a phase Ib trial using the gemcitabine pro-drug NUC-1031, designed to overcome tumor mechanisms of drug resistance, could not be supported by efficacy testing using the cytidine deaminase (CDA)-high CCA patient-derived xenograft (PDX) model." (PMID 32679791, 2020). "Whether the determination of the CDA mRNA levels and/or methylation status could be useful for predicting the clinical responses of MDS patients should be further investigated using frozen and matched tumor samples obtained at optimized periods during 5AC treatment." (PMID 31040918, 2019). "ND GBM pre-surgery saliva (NDT0) showed the exclusive characterization of peptide fragments of CDA, HOPX, FABP5, WIPF3, VOPP1, AHNAK, and DAZAP1 proteins, which, to the best of our knowledge, have not been previously identified in relation to GBM tumor." (PMID 41155285, 2025).
cancer (97 papers, 2009 to 2025). A tumor composed of atypical neoplastic, often pleomorphic cells that invade other tissues. "A ‘cool’ immunological milieu and elevated CDA levels in cancer cells were linked in a pan-cancer investigation using 16 scRNA-seq datasets." (PMID 40011298, 2025). "Mutational patterns caused by APOBEC3 cytidine deaminase activity are evident throughout human cancer genomes." (PMID 38886582, 2024). "A thorough analysis of the expression, variants, and polymorphisms of CDA and the regulation of RR gene expression can pave the way for the development of effective cancer treatments." (PMID 38275398, 2024). "Most cells can scavenge epigenome-related nucleosides and maintain genomic integrity, but cancer cells overexpressing CDA convert 5hmdC and 5fdC into variants of uridine, which accumulate in DNA and result in DNA damage and even cell death." (PMID 35999456, 2022). "We also found that Tau protein is important for the survival of CDA-deficient cells, and that CDA expression is downregulated in about 50–88% of cancer cells and tissues of different origins." (PMID 35925417, 2022). "APOBEC enzymes are a family of evolutionarily conserved cytidine deaminases and are endogenous mutagens that induce somatic driver and passenger gene mutations in human cancers through cytidine deaminase." (PMID 33925044, 2021). "APOBEC3B, an anti-viral cytidine deaminase which induces DNA mutations, has been implicated as a mediator of cancer evolution and therapeutic resistance." (PMID 32034147, 2020). "CDA upregulation decreases the cellular gemcitabine concentration, and several studies have reported that increased CDA activity associates with gemcitabine resistance in cancer cells." (PMID 35582220, 2020). "Although the sources of mutations driving oncogenesis can be many, the aim of the study was to explore the contribution of APOBEC1 cytidine deaminase to the large number of point mutations and rearrangements evidenced in many cancer genomes." (PMID 31726973, 2019). "Regardless, uracil lesions are generated not only by spontaneous deamination in FFPE blocks (artifactual mutation) but also by activation-induced cytidine deaminase in cancer (natural mutation)." (PMID 28498833, 2017). "Because a wide inter-patient variability has been observed with CDA, numerous studies have been undertaken to screen for possible mutations and polymorphisms affecting the CDA gene since the mid-70s, both in germinal cells and in cancer cells." (PMID 27007129, 2016). "This implies that CDA upregulation in cancer cells and its association with ICI resistance may impair the effectiveness of immunotherapy and antitumor responses." (PMID 40011298, 2025). "Cytidine deaminase (CDA) catalyzes the hydrolytic deamination of cytidine to uridine, and it has been proven that CDA deficiency leads to DNA damage, associating with cancer development." (PMID 35574395, 2022). "CDA deficiency, thus, identifies a new subgroup of cancers and appears to be a novel and relevant predictive marker of susceptibility to antitumor drugs, opening up new possibilities for treating cancer." (PMID 35925417, 2022). "Recent study results have demonstrated that a subclass of apolipoprotein B mRNA-editing enzyme, catalytic polypeptide-like (APOBEC) cytidine deaminase may induce mutation clusters in various types of cancer." (PMID 24748981, 2014). "Thus, our finding that CDA deficiency leads to genetic instability, and those of studies reporting constitutively low levels of CDA activity in blood, led us to hypothesize that constitutive CDA deficiency might confer a predisposition to cancer development." (PMID 35982128, 2022). "We therefore hypothesized that constitutive CDA deficiency might confer a predisposition to cancer." (PMID 35982128, 2022). "The SBS85 signature is associated with the indirect effect of induced activation of cytidine deaminase (AID), an enzyme homologous to APOBEC implicated in the development and progression of cancer." (PMID 40430005, 2025).